MAN1C1 (mannosidase alpha class 1C member 1)
Description:
Involved in the maturation of Asn-linked oligosaccharides. Trim alpha-1,2-linked mannose residues from Man(9)GlcNAc(2) to produce first Man(8)GlcNAc(2) then Man(6)GlcNAc and a small amount of Man(5)GlcNAc.
Synonyms: MAN1A3; MAN1C; HMIC; pp6318
Tractability: Antibody: UniProt predicts a signal peptide or a membrane-spanning region. PROTAC: its protein half-life has been measured.
Gene: Protein-coding gene on chromosome 1 (25,616,791 to 25,786,205, forward strand). Ensembl gene ENSG00000117643.
Subcellular location: Golgi apparatus membrane
Subcellular location (Human Protein Atlas): Nucleoplasm; Vesicles
Pathways (Reactome):
Metabolism of proteins: Progressive trimming of alpha-1,2-linked mannose residues from Man9/8/7GlcNAc2 to produce Man5GlcNAc2
Vesicle-mediated transport: Intra-Golgi traffic
Gene Ontology:
Molecular function: protein binding; calcium ion binding; mannosyl-oligosaccharide 1,2-alpha-mannosidase activity
Biological process: ERAD pathway; Golgi apparatus N-glycan mannose trimming; protein N-linked glycosylation; carbohydrate metabolic process; N-glycan processing
Cellular component: extracellular exosome; endoplasmic reticulum; Golgi membrane; membrane
Genetic constraint (gnomAD): Loss-of-function variants: 48 observed, 69.29 expected, observed/expected ratio (o/e) 0.69, 90% interval 0.55 to 0.88. The upper end of that interval is the gene's LOEUF score, 0.88, which puts it in group 3 of 6, group 1 being the genes least tolerant of losing a copy. Missense variants: 740 observed, 826.83 expected, observed/expected ratio (o/e) 0.89, 90% interval 0.84 to 0.95. Synonymous variants: 349 observed, 335.57 expected, observed/expected ratio (o/e) 1.04, 90% interval 0.95 to 1.14.
Homologues: Orthologues: chimpanzee MAN1C1 (99% identical), macaque MAN1C1 (94% identical), rat Man1c1 (89% identical), mouse Man1c1 (88% identical), pig MAN1C1 (88% identical), dog MAN1C1 (86% identical), guinea pig MAN1C1 (81% identical), tropical clawed frog man1c1 (61% identical), zebrafish MAN1C1 (47% identical), Drosophila melanogaster alpha-Man-Ia (43% identical), Caenorhabditis elegans mans-2 (39% identical), Drosophila melanogaster alpha-Man-Ic (33% identical), and 2 more. Paralogues in human: MAN1A1 (52% identical), MAN1A2 (52% identical), MAN1B1 (31% identical), EDEM2 (25% identical), EDEM1 (24% identical), EDEM3 (24% identical).
Diseases named in the same sentence as MAN1C1 in open-access papers:
MAN1C1 is named in the same sentence as 16 diseases in open-access papers, as found by Europe PMC text mining. Sharing a sentence is not in itself a finding about the gene and the disease. The quoted sentences say what the papers report.
glioma (2 papers, 2024 to 2025). A benign or malignant brain and spinal cord tumor that arises from glial cells (astrocytes, oligodendrocytes, ependymal cells). "In summary, we found that the α-1,2-mannosidase MAN1C1 was elevated in GSCs and was linked to the clinical, pathological, and molecular characteristics of gliomas." (PMID 39333557, 2024). "Our enrichment analysis demonstrated that the MAN1C1-expressing glioma cell cluster is associated with immune- and inflammatory-related genes." (PMID 39333557, 2024). "We found that high α-1,2-mannosidase MAN1C1 is associated with immunological functions and worse survival of glioma patients." (PMID 39333557, 2024). "Enrichment analysis revealed that increased MAN1C1 levels are associated with immunological and inflammatory-related genes, perhaps leading to infiltration of immune cells and dysregulated immune responses in gliomas." (PMID 39333557, 2024). "Emerging data further implicate augmented MAN1C1 expression in orchestrating immune and inflammatory gene modules, potentially fostering immune cell infiltration and dysregulation in gliomas." (PMID 40524207, 2025). "Secreted signals in MAN1C1-expressing glioma cells, such as PTN, MIF, ANXA1, MDK, and NAMPT, allowed MAN1C1 to interact with myeloid/microglial cells." (PMID 39333557, 2024). "Myeloid/microglial cells can communicate with MAN1C1-expressing glioma cells via signals produced (SPP1, GRN, PSAP, HBEGF, LGALS9, WNT5A)." (PMID 39333557, 2024). "To better understand the role of MAN1C1 in gliomas and the TME, we analyzed the scRNA-seq dataset (GSE182109) from three primary GBM samples." (PMID 39333557, 2024). "The production of signaling factors (PNT, MIF, ANXA1, and MDK) in MAN1C1-expressing glioma cells enables communication with microglial/myeloid cell clusters." (PMID 39333557, 2024). "An increase in contact strength indicates a strong interaction between MAN1C1-expressing glioma cells, other glioma cells, and myeloid/microglial cells." (PMID 39333557, 2024). "Our findings imply that MAN1C1 expression can be used to predict glioma patient response to ICB treatment." (PMID 39333557, 2024). "As myeloid/ microglial cells had the strongest interaction with MAN1C1-expressing glioma cells, we investigated the ligands and receptors involved." (PMID 39333557, 2024). "In MAN1C1-expressing glioma cells, the presence of highly glycosylated receptors, such as CD44 and integrins (ITGB1, ITGAV, ITGA8, ITGAB1) facilitates this interaction." (PMID 39333557, 2024). "According to cell-cell interaction analysis, MAN1C1-expressing glioma cells strongly interact with myeloid/microglial cell clusters." (PMID 39333557, 2024). "We found that MAN1C1 was highly expressed in gliomas with MES1-like (hypoxia-independent) gene signatures." (PMID 39333557, 2024). "MAN1C1 was overexpressed in glioma cluster 2 cells exhibiting a MES1-like cell state based on their module scores." (PMID 39333557, 2024). "The circle interaction plots depict the count and weight of the inferred high intercellular communication network between MAN1C1-expressing glioma cells and other cell clusters." (PMID 39333557, 2024). "We found that MAN1C1-expressing glioma cells interact with microglial/myeloid cells via the SPP1-CD44 signaling pathway." (PMID 39333557, 2024). "To further understand the role of MAN1C1 expression in gliomas, we conducted WGCNA on the TCGA dataset." (PMID 39333557, 2024). "We demonstrated that increased MAN1C1 expression in GSCs correlates with immunological changes and predicts poor outcomes in patients with gliomas." (PMID 39333557, 2024). "Additionally, the MAN1C1-IPS risk score is linked to somatic changes, malignant characteristics, and clinical features of gliomas." (PMID 39333557, 2024). "We demonstrated that MAN1C1 was significantly expressed in high-grade gliomas." (PMID 39333557, 2024). "These suggest that MAN1C1 is a potential biomarker for gliomas and may be important as an immunotherapeutic target for GBM." (PMID 39333557, 2024).
glioma (continued). "Our findings provide new insights into the molecular role of MAN1C1 and suggest that MAN1C1 could be a therapeutic target in gliomas." (PMID 39333557, 2024). "We believe that elevated MAN1C1 expression may affect the glycan structure and surface proteins of gliomas, influencing immune cell infiltration or evasion." (PMID 39333557, 2024). "We employed scRNA-seq to further investigate the role of MAN1C1 in gliomas and TME." (PMID 39333557, 2024). "Recently, MAN1A1 (MAN1C1 paralogue) was reported to be downregulated in CD133 + glioma stem cells, suggesting that high-mannose type N-glycan could be an enrichment signal for proneural GSC45." (PMID 39333557, 2024). "We subsequently grouped the glioma cells to further classify cells expressing MAN1C1." (PMID 39333557, 2024). "Furthermore, MAN1C1 expression is elevated in glioma patients with wild-type IDH, 1p/19q co-deletion, and an unmethylated MGMT promoter status." (PMID 39333557, 2024). "We also found that elevated MAN1C1 expression predicts worse outcomes in patients with glioma, indicating that MAN1C1 could be a potential biomarker for predicting glioma patient survival." (PMID 39333557, 2024). "Overall, our findings indicate that elevated MAN1C1 expression may contribute to immune cell infiltration in gliomas." (PMID 39333557, 2024). "First, we isolated MAN1C1-expressing glioma cells from the remaining glioma cell clusters." (PMID 39333557, 2024). "Overall, these findings suggest that MAN1C1 may play a role in immune responses and regulate tumor-related signaling pathways in gliomas." (PMID 39333557, 2024). "Furthermore, higher MAN1C1 expression predicts worse outcomes in glioma patients." (PMID 39333557, 2024). "Hence, these results suggest that elevated MAN1C1 expression may be a predictor of prognosis and OS in glioma patients." (PMID 39333557, 2024). "Moreover, MAN1C1 was substantially expressed in a portion of the glioma cell cluster." (PMID 39333557, 2024). "A MAN1C1-IPS was constructed and validated using the TCGA dataset, resulting in a considerably more accurate prediction of glioma prognosis than clinicopathological variables." (PMID 39333557, 2024). "A combined transcriptomics study of bulk, spatial, and scRNA-seq data revealed that MAN1C1 is related to MES characteristics in GBM, contributing to a poor overall prognosis in glioma patients." (PMID 39333557, 2024).
acute kidney injury (1 paper, 2021). Sudden and sustained deterioration of the kidney function characterized by decreased glomerular filtration rate, increased serum creatinine or oliguria. "Moreover, cg07242931 in MAN1C1 and cg18194850 in SUCLG2 were not only associated with eGFR, but predicted time to kidney failure or acute kidney injury." (PMID 34887417, 2021).
glioblastoma (1 paper, 2024). The most malignant astrocytic tumor (WHO grade IV). "Taken together, the findings show that MAN1C1 is a predictive biomarker in glioblastoma and could be a new target for developing immunotherapies for GBM." (PMID 39333557, 2024).
hepatic cancers (1 paper, 2020). "For instances, MGAT1, MGAT4A, and GXYLT2 are unfavorable prognostic markers, while MAN1C1, GCNT4, and STT3B are favorable markers in non-hepatic cancers." (PMID 32850363, 2020).
malignant glioma (1 paper, 2024). A grade III or grade IV glioma arising from the central nervous system. "Further research is needed to understand the correlation between mutation status and MAN1C1 expression in patients with malignant gliomas." (PMID 39333557, 2024).
renal carcinoma (1 paper, 2020). A carcinoma arising from the epithelium of the renal parenchyma or the renal pelvis. "Indeed, data obtained from two human renal cancer cell lines indicate that overexpression of MAN1C1 inhibits cell migration and decreases invasiveness." (PMID 32419574, 2020).
Sepsis (1 paper, 2025). Sepsis is defined as life-threatening organ dysfunction caused by a dysregulated host response to infection. "The key genes distinguishing sepsis from healthy conditions include B3GNT5, FUT11, ST3GAL5, MAN1C1, C1GALT1C1, and GALNT14." (PMID 39981259, 2025). "The expression trends of six Golgi-related genes (B3GNT5, FUT11, ST3GAL5, MAN1C1, C1GALT1C1, and GALNT14) aligned with the patterns observed in the hub genes from the initial sepsis dataset analysis." (PMID 39981259, 2025).
tuberculosis (1 paper, 2025). A chronic, recurrent infection caused by the bacterium Mycobacterium tuberculosis. "Transcriptomic profiling identified five metabolically significant differentially expressed genes (FHIT, MAN1C1, SLC4C7, NT5E, AKR1C3; p < 0.05) that effectively distinguish between latent tuberculosis infection (LTBI) and active tuberculosis (TB)." (PMID 40524207, 2025). "Notably, this research represents the first comprehensive identification of significant differential expression patterns of FHIT, MAN1C1, SLC4A7, NT5E, and other genes in patients with tuberculosis (TB)." (PMID 40524207, 2025).
cancer (4 papers, 2021 to 2025). A tumor composed of atypical neoplastic, often pleomorphic cells that invade other tissues. "We then examined the association between MAN1C1 expression and the seven-step cancer-immunity cycle in the TCGA cohort." (PMID 39333557, 2024). "We found that MAN1A1 and MAN1C1 were significantly downregulated in cancer tissues compared to the healthy urothelium." (PMID 40430030, 2025). "The results revealed that when MAN1C1 expression increased, the genes in various stages of the cancer-immune cycle also increased." (PMID 39333557, 2024). "Additionally, increased expression of oligomannoses in cancer has been linked to reduced expression or activity of α1,2-mannosidases, such as MAN1A1, MAN1A2, and MAN1C1." (PMID 40430030, 2025). "In contrast, a limited number of genes are predominantly downregulated throughout all cancer types, such as ST6GALNAC6, ST6GALNAC3, GALNT16 and MAN1C1." (PMID 36009354, 2022). "Interestingly, MAN1C1 is known as a tumor suppressor in KIRC and exerts protumor effects on several cancers." (PMID 34544412, 2021). "Finally, we examined the association between MAN1C1 expression and the expression of genes at different stages of the cancer-immunity cycle from the TIP website and between MAN1C1 expression and the expression of immunomodulator and chemokine genes from the TISIDB website." (PMID 39333557, 2024).
tumor (4 papers, 2020 to 2025). "In contrast, tumor purity was inversely associated with MAN1C1 expression." (PMID 39333557, 2024). "It has been suggested that MAN1C1 is a potential tumor suppressor." (PMID 32419574, 2020). "Integrated analysis of GTEx (normal, n = 171) and TCGA (tumor, n = 179) datasets revealed higher expression of CHST11, SLC16A1, RHOF, MAN1C1, SPRR1B, and ANO6 in tumors." (PMID 41346619, 2025). "To better understand the relationship between MAN1C1 expression and the tumor microenvironment (TME), we computed correlations between MAN1C1 expression and stromal, immune, ESTIMATE, and tumor purity scores." (PMID 39333557, 2024).
infection (2 papers, 2024 to 2026). The state of being infected such as from the introduction of a foreign agent such as serum, vaccine, antigenic substance or organism. "An earlier investigation revealed that -mannosidase I (MAN1C1) contributes to cellular immunity during several chronic diseases, including infection with the hepatitis B virus." (PMID 38890657, 2024).
MAN1C1 also shares sentences with these, for which no sentence is quoted: COVID-19 (1 paper); intrahepatic cholangiocarcinoma (1); kidney failure (1); leiomyoma (1); prostate carcinoma (1).